AEBP1 (AE binding protein 1)
Diseases named in the same sentence as AEBP1 in open-access papers (continued):
Sharing a sentence is not in itself a finding about the gene and the disease.
tumor (continued). "We previously showed that upregulation of adipocyte enhancer-binding protein 1 (AEBP1) in vascular endothelial cells promotes tumor angiogenesis." (PMID 37686580, 2023). "Cisplatin treatment decreased the tumor volume and tumor weight (P < 0.01), and the silencing of AEBP1 significantly enhanced the inhibition effects of cisplatin on tumor growth." (PMID 36352396, 2022). "The results suggested that AEBP1 promotes tumor growth and AEBP1 silencing contributes to suppressing tumorigenesis." (PMID 36352396, 2022). "To explore the effects of AEBP1 on clinical patients, we first investigated the expression levels of AEBP1 among normal and tumor samples in cancer patients in the TCGA database." (PMID 34938806, 2021). "Firstly, the levels of AEBP1 were analyzed of single-cell subpopulations across all tumors, including immune cells, tumor cells, and stromal cells." (PMID 34938806, 2021). "Currently, several reports suggest that AEBP1 regulates tumor progression through the following mechanisms." (PMID 34938806, 2021). "According to our qRT-PCR results for 51 pairs of GBM tissues and adjacent normal tissues, AEBP1 showed significantly higher mRNA expression in tumor tissues." (PMID 33224311, 2020). "In a very recent study, Yorozu and colleagues demonstrated that AEBP1 upregulation in endothelial cells stimulates tumor angiogenesis in CRC." (PMID 32565808, 2020). "By observing the growth rate of subcutaneous tumors, we found that tumor growth was significantly accelerated in the group with AEBP1 overexpression, while the growth of tumors in the group with AEBP1 silencing was significantly slowed down." (PMID 33224311, 2020). "AEBP1 is therefore reported to promote tumor progression in mammary epithelial cells through upregulation of TNFα secretion, thereby augmenting the Akt-mediated survival signal." (PMID 32565808, 2020). "Analysis of three ovarian datasets from SOC patients (GSE26193, GSE9891, and TCGA) identified AEBP1 as one of the top 25 genes correlated with tumor staging of SOC." (PMID 32565808, 2020). "In this study, we found that AEBP1 is highly expressed in GBM through tumor-related databases and bioinformatics analysis, which correlates with a poor prognosis for the patients." (PMID 33224311, 2020). "This study further affirms the ability of AEBP1 to promote tumor progression via the canonical NF-κB pathway." (PMID 32565808, 2020). "Li and colleagues investigated the potential role of AEBP1 in tumor progression of CRC by analyzing CRC tissues from randomly selected patients." (PMID 32565808, 2020). "U251 cells stably overexpressing AEBP1 or U87 cells stably silencing AEBP1 after lentiviral transfection were injected subcutaneously to recapitulate subcutaneous tumor models." (PMID 33224311, 2020). "Immunohistochemical staining of tumors revealed the expression of several CAF- and EMT-related proteins in the tumor microenvironment, including AEBP1." (PMID 32565808, 2020). "Subsequently, we verified the high expression of AEBP1 in GBM tissues and cell lines and found that the expression of AEBP1 was closely related to the tumor size of GBM." (PMID 33224311, 2020). "In 786-O primary tumor cell line we observed decrease expression of genes of insulin-associated proteins (IRS2, CBL), transcription regulators (AEBP1), PI3 kinase signaling (AKT1, BCL2L1) as well as lipid metabolism genes (ACOX1)." (PMID 30929166, 2019). "Elevated AEBP1 expression was significantly correlated with poor overall survival in patients with both early-stage (Tumor, Node, Metastases (TNM) TNM I and II) and late-stage (TNM III and IV) GC." (PMID 30097586, 2018). "Five genes demonstrated complete loss or downregulation of expression in at least 20% of RCC tumours (GCM2 (80% of RCC), RGS7 (46.7%), TMEM74 (46.7%), NEFM (20%) and AEBP1 (20%))." (PMID 24034811, 2013). "Based on these insights, we hypothesized that AEBP1/ACLP expression in CAFs contribute to the stiffness of tumor tissues." (PMID 41373631, 2025).
tumor (continued). "In conclusion, our study revealed that AEBP1 expression is strongly correlated with collagen expression across multiple cancers and that AEBP1 is predominantly expressed by CAFs, where it contributes to the enhancement of tumor stiffness." (PMID 41373631, 2025). "Given that stromal stiffness and immune suppression are intimately linked in many refractory cancers, interventions that reduce AEBP1/ACLP activity could potentially restore tissue elasticity and improve cytotoxic T-cell access to tumor nests." (PMID 41373631, 2025). "Pharmacologic targeting of AEBP1/ACLP or its downstream effectors may thus provide a strategy to remodel the fibrotic tumor stroma and enhance immune checkpoint inhibitor efficacy." (PMID 41373631, 2025). "Similarly, SSZ treatment significantly suppressed the volume and weight of tumor compared with the sh-NC group, which was more significant in the sh-AEBP1 + SSZ group than in the sh-NC + SSZ group (P < 0.01)." (PMID 36352396, 2022). "In recent years, the role of AEBP1 in tumor regulation has gradually attracted people’s attention." (PMID 36523769, 2022). "In these results, AEBP1 was closely related to inflammation response and immune response which might lead to immune escape of tumor cells." (PMID 34373835, 2021). "In addition to aberrant expression in tumor tissues, AEBP1 also exhibited poor prognostic survival in COAD." (PMID 34938806, 2021). "Moreover, a higher TNM stage (stage III) showed stronger AEBP1 expression than a lower stage (stage I) of tumor samples, suggesting that AEBP1 mRNA expression levels were correlated with TNM stages of COAD patients." (PMID 34938806, 2021). "Therefore, AEBP1 promotes tumor progression in GBM through its oncogenic properties, and its tumorigenic role in GBM can be extended to many other tumor types." (PMID 33224311, 2020). "AEBP1 may display similar effects in CAFs, enhancing the metastatic features and proliferative abilities of cancer cells within the tumor microenvironment." (PMID 32565808, 2020). "Interestingly, AEBP1 expression in human umbilical vein endothelial cells (HUVECs) was shown to be increased by tumor-conditioned medium derived from CRC cells as well as by direct coculture with CRC cells." (PMID 32565808, 2020). "AEBP1 can promote proliferation, metastasis, angiogenesis, and inflammation and suppress apoptosis both in vitro and in vivo; therefore, it acts as an oncogene to promote tumor progression." (PMID 33224311, 2020). "AEBP1 was shown to be methylated in several renal cell carcinoma cell lines and tumor samples." (PMID 32565808, 2020). "In terms of our findings, we may need to take into consideration the expression levels of AEBP1 in patients’ tumor samples when planning clinical trials of MTOR inhibitors on GBM or evaluating clinical responses of MTOR inhibitors in the treatment of GBM." (PMID 32938364, 2020). "Moreover, the expression of AEBP1 was found to be closely related to tumor size based on the clinical data of the patients." (PMID 33224311, 2020). "Identifying miR-214 as a negative regulator of AEBP1 may lead to the therapeutic targeting of AEBP1 and suppression of tumor progression in CRC patients." (PMID 32565808, 2020). "In other words, AEBP1 expression positively correlated with the progression of tumor stage." (PMID 32565808, 2020). "Notably, recent studies have illustrated an important role of AEBP1 in tumorigenesis and tumor progression." (PMID 30097586, 2018). "Moreover, Aebp1 induces NF-κB activity which leads to macrophage inflammatory responsiveness and affects tumor cell growth and survival." (PMID 27092172, 2016). "Importantly, AEBP1 silencing suppressed tumor growth in vivo." (PMID 36352396, 2022). "Moreover, AEBP1 silencing suppressed tumor growth in the tumor xenograft mice models." (PMID 36352396, 2022). "Thus, a larger study may further substantiate AEBP1 as a critical CAF-related biomarker that promotes tumor progression and invasiveness in cutaneous malignant tumors." (PMID 32565808, 2020).
tumor (continued). "Since AEBP1 mediates the activation of NF-κB signaling, and since the uncontrollable activation of NF-κB promotes oncogenesis, it is suggested that AEBP1 overexpression may promote tumor progression via upregulation of NF-κB pathway." (PMID 32565808, 2020). "Thus, AEBP1 plays a cancer-promoting role in many tissues and may be a potential target for tumor therapy." (PMID 33224311, 2020). "In contrast, in a recent report depicting six master regulators (AEBP1, HOPX, PRRX1, SNAI2, ZEB1, ZEB2) of the TCGA “mesenchymal” subtype, they employed a network-based strategy to uncover the molecular mechanism underlying the discrete mesenchymal subtype in whole tumor tissues of serous OC." (PMID 27081703, 2016). "This suggests that AEBP1/ACLP represents a promising therapeutic target through which to remodel the tumor microenvironment and enhance anti-tumor immunity." (PMID 41373631, 2025). "To further generalize these findings, we assessed the correlation of AEBP1 expression with CAF markers (ACTA2, FAP, and PDGFRB) and representative collagen family genes across 32 TCGA tumor types." (PMID 41373631, 2025). "When HSMMs were cultured for 72 h in tumor conditioned medium (TCM) prepared with an OSCC cell line (SAS), AEBP1 expression was upregulated." (PMID 39521917, 2024). "For ADAMTS12, AEBP1, COL10A1, COL11A1, CXCL11, EPPK1, and WNT7B, their expression values were higher in tumor samples than in normal samples." (PMID 35505821, 2022). "According to the Human Protein Atlas database, we found that the protein expression levels of AEBP1, BGN, and TAGLN in tumor tissues were higher than those in normal tissues." (PMID 36523769, 2022). "Knockdown of ACT001 target AEBP1 inhibits AKT phosphorylation and tumor cell proliferation to exert antitumor effects." (PMID 37786890, 2022). "The protein expression levels of AEBP1, BGN, and TAGLN in tumor tissues were higher than those in normal tissues." (PMID 36523769, 2022). "In the previous researches, it was defined that AEBP1 was overexpressed in GBM and related with many types of tumor such as colon adenocarcinoma and gastric cancer." (PMID 34373835, 2021). "We observed that there were higher mRNA expression levels of AEBP1 in all stages (stage I, stage II, stage III, and stage IV) of tumor samples than in normal samples." (PMID 34938806, 2021). "AEBP1 was reported to be overexpressed in the astrocyte cell line, U78MG, and its overexpression was believed to be indicative of tumor progression." (PMID 32565808, 2020). "Upregulated AEBP1 in GBM promotes GBM cell proliferation, migration, and invasion and facilitates tumor growth in vivo by activating the classical NF-κB pathway." (PMID 33224311, 2020). "AEBP1 promotes GBM cell proliferation, migration, and invasiveness and facilitates tumor growth in vivo by activating the classical NF-κB pathway." (PMID 33224311, 2020). "Consistently, a coexpression analysis of 331 COAD samples using the ChIPBase v2.0 demonstrated a positive relationship between AEBP1 level and the expression of MMP-2, vimentin, TWIST, ZEB1, ZEB2, and SNAIL1, inducers of tumor growth, invasion, and metastasis." (PMID 32565808, 2020). "Collectively, these results indicate that AEBP1 overexpression induces the EMT process by suppressing E-cadherin expression, thereby enhancing tumor progression in COAD." (PMID 32565808, 2020). "In univariate analysis, tumor location (P = 0.041), T stage (P < 0.001), N stage (P = 0.001), M stage (P < 0.001), TNM stage (P < 0.001) and AEBP1 expression (P = 0.001) were significantly associated with prognosis." (PMID 30097586, 2018). "AEBP1 (ACLP), another ECM protein, is secreted by fibroblasts and myofibroblasts and has been shown to be involved in wound healing and tumor ECM remodeling." (PMID 29245949, 2017). "Using the GEPIA2 platform, we analyzed TCGA-STAD data for expression of AEBP1, which showed higher expression in tumor samples than in normal samples." (PMID 40296906, 2025).
tumor (continued). "Downregulation of AEBP1 in tumour endothelial cells in vitro reduced levels of angiogenesis-related genes, POSTN and AQP1, suggesting that AEBP1 may regulate new blood vessel formation." (PMID 39930483, 2025). "Conversely, TQ treatment resulted in the downregulation of several genes overexpressed in GBM cells, including potential oncogenes like AEBP1, MIAT, GHR, LMO1, ELF3, and genes involved in tumor proliferation and migration such as EPHA4, COL3A1, PCDH10, ROBO1, ADAMTS5, PCDH18, ST8SIA1." (PMID 39874307, 2025). "Next, we analyzed the expression of AEBP1-correlated gene BGN (R = 0.901, p < 0.001) in single-cell RNA-seq data, and found that BGN was expressed in fibroblasts of normal tissues, and when cancer occurred, it was mainly expressed in tumor cells." (PMID 40296906, 2025). "Meanwhile, AEBP1 silencing enhanced the effects of SSZ on levels of LIP and Fe2+, lipid peroxidation, as well as the expression levels of ferroptosis-related genes in the tumor xenograft mouse models." (PMID 36352396, 2022). "The results suggested that silencing of AEBP1 might interact with the JNK / P38 / ERK pathway, thereby suppressing tumor progress." (PMID 36352396, 2022). "ACT001 in combination with SHP099 further reduced tumor burden, p-AKT, the expression of AEBP1, Ki-67, hNestin, and extended survival to a greater extent than ACT001 treatment alone, suggesting that the combination of ACT001 and SHP099 synergizes to extend the survival in our GSC xenograft model." (PMID 33391492, 2021). "When signatures from plasma- and ascites-derived sEVs were compared we found significant differences in expression of COL5A1, AEBP1, TIMP3, and ACTB at week 3 of tumor progression, suggesting that ascites-derived sEVs are likely a stronger indicator of tumor presence compared to plasma-derived sEVs." (PMID 34868914, 2021). "Importantly, compared to normal tissues, extremely high correlations were observed among AEBP1, BGN, POST, and FAP in COAD, suggesting that the STMERN specifically formed in tumor tissues." (PMID 34239578, 2021). "To better understand the relationship between AEBP1 expression and clinical features, we assessed AEBP1 levels in different TNM stages and nodal metastasis status, in which higher TNM stages and more nodal metastasis exhibit faster tumor progression and greater metastatic ability." (PMID 34938806, 2021). "Tumor-related databases and bioinformatics analysis revealed that AEBP1 was highly expressed in GBM and indicated poor outcome of patients; its high expression that was also confirmed in GBM tissues and cell lines was closely related to the tumor size." (PMID 33224311, 2020). "In addition to the genes discussed, there were additional stromal genes identified by the NN analysis, including CDH11, OLML3, FSTL1, AEBP1, VCAN, previously reported to correlate with tumor progression and metastasis in various cancers." (PMID 27128408, 2016). "Our above results suggest that since AEBP1 cooperates with key transcription factor TCF3 downstream of the Wnt signaling in GC, the knockdown of AEBP1 may enhance the inhibitory effect of Wnt pathway inhibitors on tumor metastasis." (PMID 40296906, 2025). "Finally, to explore whether AEBP1-mediated EMT was related to the tumor microenvironment (TME), we examined AEBP1 expression levels at the single-cell levels." (PMID 34938806, 2021). "Moreover, AEBP1 silencing was accompanied by impaired nuclear translocation of NF-κB/p65 and inhibited expression of CXCR4 and ICAM-1, downstream targets of NF-κB signaling that are involved in tumor growth, invasion, and metastasis." (PMID 32565808, 2020).
tumor (continued). "Although Sasaki and colleagues have identified AEBP1 as a possible CAF biomarker, the specific role of AEBP1 in this tumor microenvironment was not characterized." (PMID 32565808, 2020). "Upregulation of AEBP1 was positively correlated with T stage (P = 0.005), N stage (P = 0.005) and TNM stage (P = 0.004), but not with sex (P = 0.504), age (P = 0.453), tumor location (P = 0.603) or histological grade (P = 0.950)." (PMID 30097586, 2018). "Expression of genes such as AEBP1, SNAI1, and LOX similarly increased after the first week of tumor progression, although these changes could not be quantitatively compared to week 1 due to undetermined Cq values at this time point." (PMID 34868914, 2021).